HES6 (hes family bHLH transcription factor 6)
Diseases named in the same sentence as HES6 in open-access papers (continued):
Sharing a sentence is not in itself a finding about the gene and the disease.
breast carcinoma (continued). "In this study, we investigated the function of Hes-6 in breast cancer and tested the hypothesis that Hes-6 enhances breast cancer cell proliferation and is regulated by estrogen." (PMID 19891787, 2009). "Here we identify Hes-6 as a novel estrogen-regulated gene in breast cancer." (PMID 19891787, 2009). "Furthermore, Hes-6 is a novel estrogen-regulated gene in breast cancer cells." (PMID 19891787, 2009). "In addition, it is possible that repression of Hes-6 could be important for the breast cancer-suppressive effects of tamoxifen." (PMID 19891787, 2009). "We identify a novel interaction between HES6 and E2F1 and E2F1 and the AR and show enhancement of E2F1 activity that seems to result from protein complex formation rather than increased E2F1 expression as previously found in breast cancer." (PMID 24737870, 2014). "The estrogen-dependent, ERα-positive T47D and MCF-7 cells contained low levels of Hes-6, in comparison with the more-aggressive, ERα-negative breast cancer cell lines MDA-MB-231 and SKBR3, which contained 4 to 10 times higher levels of Hes-6 mRNA." (PMID 19891787, 2009). "We found that Hes-6 expression was significantly higher in the high-grade, estrogen receptor (ER)α-negative SKBR3 and MDA-MB-231 cells compared with the ERα-positive, non-metastasizing T47D and MCF-7 breast carcinoma cells." (PMID 19891787, 2009).
uveal melanoma (7 papers, 2021 to 2024). A melanoma derived from melanocytes of the uveal tract. "HES6 has been recently implicated in uveal melanoma progression, which is the main primary intraocular malignancy in adults and the second most common melanoma." (PMID 35673577, 2022). "Interestingly, in our study HES6 was strongly co-expressed with ERFE in uveal melanoma, which was associated with distant metastasis." (PMID 36675239, 2023). "Our study showed a strong positive correlation between ERFE and HES6 expression in thyroid cancer, uveal melanoma, and testicular germ cell tumors." (PMID 36675239, 2023). "They deciphered a gene regulatory network underlying an invasive and poor prognosis state driven in part by the transcription factor HES6, which is a valid target to stop uveal melanoma progression." (PMID 37612741, 2023). "Their findings identified that HES6 increases the aggressive potential and motile capacity of primary uveal melanoma both in vitro and in vivo." (PMID 37612741, 2023). "In this review, we focus on the role, regulation and mechanisms of action of HES6, with a special focus on cancers including uveal melanomas." (PMID 35673577, 2022). "Altogether, these data indicate a key role for NOTCH activation and HES6 in uveal melanoma progression." (PMID 35673577, 2022). "Our single-cell analysis of primary uveal melanomas identified a list of HES6 effectors (HES6 regulon)." (PMID 35673577, 2022). "HES6 contributes to the metastatic phenotype in tumors, including uveal melanomas, and represents a potentially important avenue of research toward uncovering therapeutic targets." (PMID 35673577, 2022). "They demonstrated that HES6 inhibition by siRNA can prevent primary uveal melanoma cells to form a colony, which suggests that HES6 may be a validated siRNA therapy target." (PMID 37138096, 2023). "Further experiments indicated that HES6 might be a valid target to limit uveal melanoma cell proliferation and migration." (PMID 37612741, 2023). "HES6 also emerged as a therapeutic target in uveal melanoma cells." (PMID 35673577, 2022). "We summarize the role of HES6 in cancers with a focus on uveal melanoma." (PMID 35673577, 2022). "Furthermore, HES6 knockdown inhibited uveal melanoma cell migration induced by DLL4, one of the five NOTCH ligands." (PMID 35673577, 2022). "Whether Wnt/β-catenin indeed lies downstream of HES6 in uveal melanoma cells and whether Wnt/β-catenin inhibitors prevent HES6 effects on proliferation and migration or MYC expression remain to be investigated." (PMID 35673577, 2022). "As revealed from the single‐cell RNA sequencing results, HES6 could stimulate the metastasis in primary uveal melanoma." (PMID 35934844, 2022). "Besides, HES6 was identified as a driver of metastasis in primary uveal melanoma by scRNA-seq, suggesting that HES6 may represent an actionable target of this tumor." (PMID 34722635, 2021). "In addition, one study based on single cell sequencing reported that HES6 has critical tumorigenic properties downstream the NOTCH signaling pathway and favors motile phenotype of primary uveal melanoma cells." (PMID 36675239, 2023). "Whether HES6 favors a pseudo-EMT and a stem cell phenotype in uveal melanoma cells remains to be determined." (PMID 35673577, 2022). "Thus, targeting HES6 through the PROTAC approach may represent a potential therapeutic strategy for the treatment of cancers, including uveal melanomas." (PMID 35673577, 2022).
prostate tumour (4 papers, 2008 to 2015). "Based on our identification of novel proteins associated with the NE lesions and NE prostate tumors we assessed expression of Hes6 and Sox9 in tissue specimens." (PMID 21037926, 2010). "In these studies we have focused on assessing three genes: Hes6, Sox9 and Jmjd1a, which were implicated in prostate tumors, and were shown (by us and others) to be regulated by HIF." (PMID 21037926, 2010). "The ubiquitous HES5 silencing in tumours cells may therefore potentiate (or de-repress) HES6 expression in prostate tumours." (PMID 25560400, 2015). "In this model, we predict that i) HES5 expression in benign epithelial cells contributes to HES6 repression and ii) HES5 promoter methylation and silencing in prostate tumours potentiates AR activation of HES6 to start an oncogenic feed-forward transcriptional signalling network." (PMID 25560400, 2015).
Hepatic steatosis (3 papers, 2017 to 2025). Steatosis is a term used to denote lipid accumulation within hepatocytes. "Hes6 plays a complementary role in circadian regulation by antagonizing the expression of Hes1 and has been shown to attenuate hepatic steatosis." (PMID 41007411, 2025). "Thus, HES6 may play a significant role in the development of hepatic steatosis during PN." (PMID 40015320, 2025). "This highlights the delicate position of SHP in the development of hepatic steatosis, inhibiting RXR/LXR-ChREBP/SREBP-1c-mediated DNL, while at the same time promoting DNL via the HES6-HNF4α-PPARγ pathway." (PMID 29286303, 2017). "The absence of SHP protects mice from diet-induced hepatic steatosis, suggesting a most prominent role for the HES6-HNF4α-PPARγ axis, which is activated by atRA and RARα." (PMID 29286303, 2017).
hepatocellular carcinoma (3 papers, 2017 to 2025). A malignant tumor that arises from hepatocytes. "High expression level of HES6 is positively correlated with clinical severity and poor prognosis of people with hepatocellular carcinoma." (PMID 29050307, 2017). "HES6, which is highly expressed in hepatocellular carcinoma, promotes tumor cell proliferation." (PMID 29050307, 2017). "In human hepatocellular carcinoma, Notch2 regulates the stemness of liver CSCs via upregulation of NRARP, HES1 and HES6." (PMID 30285832, 2018).
glioblastoma (2 papers, 2022 to 2025). The most malignant astrocytic tumor (WHO grade IV). "Similarly, the enrichment of HES6 and MYC motifs in brain-specific promoters provides mechanistic insights into neuroblastoma and glioblastoma pathogenesis as these factors are known to be dysregulated in aggressive brain cancers." (PMID 41279024, 2025).
melanoma (2 papers, 2018 to 2022). A malignant, usually aggressive tumor composed of atypical, neoplastic melanocytes. "When comparing the FFPE with the FF melanoma signature, two candidate genes were missing (esophageal cancer–related gene 2 [ECRG2] and hairy and enhancer of split 6 [Drosophila] [HES6]) and guanylate binding protein–4 (GBP4) was included." (PMID 31360859, 2018). "In addition, we identified Mesenchyme (COL1A1+), Endothelium (SOX18+, KDR+), proliferating cells (TOP2A+, MKI67+), and some off‐target cells; Glial (MSX1+, SOX2+), Melanoma (PMEL+, PLP1+), and Neuron (DLL3, HES6)." (PMID 35322595, 2022).
myeloma (2 papers, 2016 to 2023). "Representative images and correlation analyses of the percentage of MM cells and JAG1, JAG2, HES6 in MM cells, and HES6 in NM non-myeloma cells are reported here." (PMID 37834003, 2023). "The results of these analyses revealed statistically significant positive correlations between the percentage of MM cells in the BMBs, the expression of both JAG1 and JAG2, and the activation of NOTCH signaling in myeloma (HES6 MM) as well as in non-myeloma cells (HES6 NM)." (PMID 37834003, 2023).
alveolar rhabdomyosarcoma (1 paper, 2017). A rapidly growing malignant mesenchymal neoplasm. "Besides, HES6 also promotes the motility of alveolar rhabdomyosarcoma cells." (PMID 29050307, 2017).
astrocytomas (1 paper, 2020). "In a specific subset of astrocytomas, upregulation of Dll1 leads to an increased expression of HES6." (PMID 32796631, 2020). "In some astrocytomas, for instance, the DLL1 ligand is upregulated, resulting in higher activation of Hes6." (PMID 32796631, 2020).
breast tumor (1 paper, 2009). "In Hes-6-expressing T47D cells, Hes-6 ectopic expression was shown to stimulate cell proliferation in vitro as well as breast tumor growth in xenografts." (PMID 19891787, 2009).
colon cancers (1 paper, 2009). "In an experimental mouse model of colon cancer, several genes were upregulated in metastases, but the only gene that was upregulated in all metastases compared with their primary tumor was Hes-6." (PMID 19891787, 2009). "Elevated levels of Hes-6 have been found in prostate and colon cancers compared with normal tissue, where the expression is low." (PMID 19891787, 2009).
colorectal tumors (1 paper, 2023). "In addition, a previous study indicated that miR-5001 expression was low in colorectal tumors and downregulation of miR-5001 that targets HES6 gene promoted cell proliferation." (PMID 36859458, 2023).
gastric cancer (1 paper, 2025). A primary or metastatic malignant neoplasm involving the stomach. "However, the precise role and underlying mechanisms of Hes6 in gastric cancer initiation and progression remain poorly understood." (PMID 42290656, 2025). "Collectively, these findings offer valuable insights into the regulatory mechanisms underlying gastric cancer progression, highlighting the potential of transcriptional cofactors, such as Hes6, in PI3K/AKT signaling as promising targets for therapeutic intervention in gastric cancer." (PMID 42290656, 2025). "Functionally, Hes6 mediates gastric cancer cells to obtain stronger proliferation, migration, and invasion abilities by activating the PI3K/AKT signaling pathway, thereby accelerating tumor progression." (PMID 42290656, 2025). "In this study, we demonstrate that Hes6 expression is significantly up-regulated in gastric cancer tissues, with elevated levels of Hes6 correlating with poor prognosis in certain patient cohorts." (PMID 42290656, 2025).
leiomyoma (1 paper, 2017). A well-circumscribed benign smooth muscle neoplasm characterized by the presence of spindle cells with cigar-shaped nuclei, interlacing fascicles, and a whorled pattern. "Lastly, we confirmed that levels of transcript encoding HES6 (P < 0.05), ZBTB16 (P < 0.02), ITPKA (P < 0.05), and CORIN (P < 0.05) were significantly higher in specimens of luteal phase leiomyomas than proliferative phase specimens." (PMID 28637297, 2017).
leukemia (1 paper, 2013). A malignant (clonal) hematologic disorder, involving hematopoietic stem cells and characterized by the presence of primitive or atypical myeloid or lymphoid cells in the bone marrow and the blood. "In contrast, Notch1 and Notch2 genes were un-methylated in any of the leukemia cell lines and normal controls, while DLL1, DLL3, DLL4 and Hes6 showed only low levels of methylation (9–27%) in these leukemia cell lines." (PMID 23637910, 2013).
lung carcinoma (1 paper, 2015). "Two other genes previously implicated in lung cancer, P2RY14 and PAPPA 41,42, were also expressed at significantly higher levels when HES6 was overexpressed." (PMID 25864518, 2015).
metastatic cancers (1 paper, 2009). A carcinoma which has spread from the original site of growth to another anatomic site. "Hes-6 is a member of the basic helix-loop-helix (bHLH) family of transcription factors, and its overexpression has been reported in metastatic cancers of different origins." (PMID 19891787, 2009).
metastatic colorectal cancer (1 paper, 2022). "HES6 was found to be up‐regulated only at the transcriptional level in a xenograft model of metastatic colorectal cancer." (PMID 35934844, 2022).
neuroendocrine tumors (1 paper, 2020). "HES6 is highly expressed in metastatic prostate adenocarcinomas and required for the hypoxia-mediated neuroendocrine phenotype, the metastasis of prostate adenocarcinomas, and the formation of neuroendocrine tumors." (PMID 33681178, 2020).
testicular germ cell tumor (1 paper, 2023). A germ cell tumor arising from the testis. "GSEA results indicated that the ERFEhigh status was associated with activated NOTCH-related signaling in thyroid cancer and testicular germ cell tumors, and HES6 overexpression was shown to contribute to overactivated NOTCH signaling." (PMID 36675239, 2023).
tumor (24 papers, 2008 to 2025). "In turn, HES6 immunoreactivity was associated with VEGF-A expression in non-tumor cells and MVD, suggesting that Notch activation in stromal cells contributes to induce angiogenesis." (PMID 32932949, 2020). "Allowing for differences in array coverage, we found that genes on this HES6-associated signature list were consistently enriched in DEG lists comparing metastatic or castrate-resistant tumours with benign or normal tissue." (PMID 24737870, 2014). "Expression of Hes-6 caused a significant increase in both tumor weight and size at both 7 and 14 days." (PMID 19891787, 2009). "Using the GEPIA2 database, we compared tumor tissues from TCGA with normal tissues from GTEx and found that SRD5A1, FUT8, and HES6 were significantly overexpressed in tumor tissues." (PMID 40729369, 2025). "Previous studies have indicated that Hes6 expression is elevated in several malignant tumors, contributing to the enhanced proliferation and invasion of tumor cells." (PMID 42290656, 2025). "Intratumoral heterogeneity was also evident in this analysis as for example characteristic marker genes for aNSCs (Hes6), TACs (Ube2c) and NBs (Stmn2) are expressed to different extents in the different tumor cell populations." (PMID 37407554, 2023). "We found a strong positive correlation among the Jagged ligand levels in MM cells and Notch signaling activation (HES6 expression) in MM cells, as well as in nearby non-tumor stromal cells." (PMID 32932949, 2020). "Jagged1 and Jagged2 expressed in the MM cells correlated with the HES6 expression in non-tumor cells (r = 0.5673 and r = 0.5516, respectively), confirming a role of MM cell-derived Jagged in activating the Notch signaling in stromal cells." (PMID 32932949, 2020). "We found that the expression levels of NOTCH2, HEY1, and HES6 were lower in lncAKHE-silenced HCC cell-derived tumor tissues than in control tumor tissues, whereas YEATS4 expression was not affected." (PMID 29706630, 2018). "Summarily, our study shows that lncSHRG is able to promote cell proliferation and tumor propagation through SATB1/HES6 signaling in HCC." (PMID 29050307, 2017). "Expectedly, C8orf4-deficient tumours showed elevated expression levels of NOTCH2 target genes such as HEY1, HES6 and NRARP." (PMID 25985737, 2015). "Knock-down of HES6 by lentiviral shRNA in C4-2b cells led to significant attenuation of tumour growth in both full and castrated conditions." (PMID 24737870, 2014). "HES6 levels are found to be raised in several independent clinical datasets comparing aggressive disease (metastases or CRPC) with primary tumour and benign disease." (PMID 24737870, 2014). "Most recently, work demonstrating the cooperation of HIF-1α and FoxA2 in metastatic neuroendocrine prostate cancer has identified HES6 as an important factor in the development of these tumours." (PMID 24737870, 2014). "The Hes-6-expressing T47D cells were transplanted into immunodeficient mice to study effects on tumor growth." (PMID 19891787, 2009). "Overexpression of HES6 was adequate to sustain normal tumor development after castration." (PMID 37569304, 2023). "The reduced motile ability of these tumor cells following HES6 knockdown may in part result from an interruption of NOTCH signaling." (PMID 35673577, 2022). "However, HES5 is also a WNT/β-catenin signaling target gene and tumor suppressor, while HES6 has been shown to be an oncogene and activator of WNT/β-catenin signaling." (PMID 32575464, 2020). "Furthermore, we checked the protein levels of NOTCH2, YEATS4, HEY1, and HES6 in tumor tissues of the xenograft experiment." (PMID 29706630, 2018). "We found that SATB1 and HES6 expressed higher in tumor tissues than in peritumor cells." (PMID 29050307, 2017). "Moreover, the expression levels of NRARP, HEY1 and HES6 in tumours are positively correlated with clinical severity and prognosis of HCC patients." (PMID 25985737, 2015).
tumor (continued). "The hypoxia-Notch gene subset (HIF-1α/PGK1/VEGF/CA9/OPN-Notch1/Dll1/Hes1/Hes6/Hey1/Hey2) identified by us might hold prognostic implication and offer new opportunities in tumor sub-classification and targeted therapy." (PMID 25734817, 2015). "Overexpression of HES6 was sufficient to maintain normal tumour growth after castration." (PMID 24737870, 2014). "In this context, HES6 may enhance tumour initiation by supporting expression of CD24." (PMID 25864518, 2015). "Hence, HES6 might also contribute to tumor progression by preventing efficient antitumor immunity." (PMID 35673577, 2022). "IHC staining also showed that lncAKHE depletion led to reduced expression of HES6 and HEY1 in lncAKHE-silenced tumor tissues." (PMID 29706630, 2018). "Consistently, high expression levels of HEY1, HES6 and NRARP in HCC tumours were validated by Zhang's cohort (GSE25097)." (PMID 25985737, 2015). "Altogether, these data suggest the existence of a network involving HES6, MYC and HIF-1a that may fuel tumor progression." (PMID 35673577, 2022). "We observed that HEY1, HES6 and NRARP were highly expressed in the tumour tissues of HCC patients." (PMID 25985737, 2015). "Finally, our model suggests that in tumour cells harbouring an ERG gene fusion iii) AR activation of the ERG fusion gene creates a dynamic negative feedback loop impacting on both the AR and HES6, creating a more complex transcriptional network." (PMID 25560400, 2015).